IL1B (interleukin 1 beta)
Diseases named in the same sentence as IL1B in open-access papers (continued):
Sharing a sentence is not in itself a finding about the gene and the disease.
atherosclerosis (continued). "The CANTOS study provided definitive prove that tackling inflammation by blocking IL-1β with the monoclonal antibody canakinumab can be a successful strategy to reduce atherosclerosis progression." (PMID 31191522, 2019). "The NLRP3 inflammasome is clearly involved in the pathogenesis of diabetes, atherosclerosis, and infectious disease due to the secretion of IL-1β and IL-18 from this complex." (PMID 30616678, 2019). "In the process of atherosclerosis, proinflammatory factors, including IL-1β and IL-8, are expressed by ox-LDL-stimulated endothelial cells and VSMCs, which, in turn, activate macrophages, resulting in amplification of the inflammatory response." (PMID 31310065, 2019). "The IL-1β pathway is a well-recognized target in many inflammatory diseases, including atherosclerosis, a plaque formation-driven narrowing of blood vessels which can lead to devastating heart attacks and strokes." (PMID 31723548, 2019). "The Canakinumab Anti-Inflammatory Thrombosis Outcome Study (CANTOS) was one of the clinical studies that concentrated on blocking the IL1B proinflammatory activity for atherosclerosis therapy." (PMID 31780867, 2019). "The linear random effect model allowed us to pinpoint other possible effects of DNT5 (adipose tissue expression of Il6, Il1β, Ccl2, atherosclerosis in the artic conduit, hepatic expression of Srebp1c and Acaca)." (PMID 30692584, 2019). "IL1B acts as not only a local vascular but also a systemic contributor in atherosclerosis progression." (PMID 31780867, 2019). "After the success of the treatment with an anti-IL-1β antibody, efforts to target the immune system to counteract atherosclerosis are on the rise and potential new strategies to target immunity and inflammation are being envisioned." (PMID 31191522, 2019). "The finding of reduced macrophage accumulation in atherosclerotic lesions and less arterial expression of IL1β in μMT−/− ApoE−/− mice is consistent with the reduced inflammation in atherosclerotic lesion, and decreased atherosclerosis in μMT−/− ApoE−/− mice." (PMID 31998318, 2019). "Both cytokines are involved in atherosclerosis progression in mice as TNFα promotes atherosclerosis and IL-1β knockout mice have smaller and less severe atherosclerotic lesions." (PMID 31461490, 2019). "As shown, LDL-C induces inflammasome activation, leading to the production of IL-1β and IL-18, which accelerate atherosclerosis." (PMID 31672136, 2019). "Cholesterol crystal-mediated inflammasome activation and IL-1β production is also involved in chronic inflammation during atherosclerosis." (PMID 31202985, 2019). "Another study that used a low dose of rivaroxaban (28.5 ng/mL in plasma) was able to attenuate progression of atherosclerosis by roughly 25%, as well as reduced inflammation, as reflected by decreased IL-1β, MCP-1, and TNF-α mRNA and protein levels." (PMID 30846818, 2019). "During atherosclerosis progression, inflammatory cytokines, such as interleukin-1β (IL-1β) and tumor necrosis factor α (TNFα), are involved in vascular remodeling." (PMID 31735914, 2019). "The secretion of the inflammatory cytokine IL-1β by M1 macrophages has been shown to be a major driver of persistent inflammation and the pathogenesis of diabetes, atherosclerosis, and sterile inflammation." (PMID 31747961, 2019). "Increased interaction of various ligand-receptor pairs including Ccl2-Ccr2, Ccl7-Ccr2, and Il1b-Il1r2 between Mesen II and inflammatory cells in ApoE−/− adventitia further implied the participation of Mesen II in early development of atherosclerosis." (PMID 30943771, 2019). "As shown by the gene correlation network, Cxcl2 and Il1b,43,44 2 important cytokines in atherosclerosis were included in the pink module." (PMID 30943771, 2019). "In this study, we found that plasma anti-TNFα and anti-IL1α IgG levels were significantly increased in patients with atherosclerosis compared with control subjects, and an increase in anti-IL1β IgG level was found in female patients." (PMID 30479572, 2018).
atherosclerosis (continued). "More recently, TFEB overexpression was shown to reverse the gradual decline in the autophagy–lysosome system that occurs in lipid loaded cells with dysfunctional lysosomes, abolishing apoptosis and reducing IL-1β production, and consequently atherosclerosis." (PMID 29997514, 2018). "Recent studies have shown that the NLRP3 inflammasome and IL-1β/IL-18 play important roles in gout, rheumatoid arthritis, atherosclerosis, DM, and oxalate-related nephropathy diseases." (PMID 29929501, 2018). "Several inflammatory cytokines, such as TNF-α, IL-1β and IL-6, have been shown to induce VSMCs proliferation/migration and hypertrophic response, which can contribute to the development of atherosclerosis." (PMID 29728095, 2018). "The NLRP3 inflammasome is reported to recognize multiple endogenous danger signals and trigger the release of proinflammatory cytokines including active IL-1β, thus contributing to many diseases such as atherosclerosis and T2 diabetes." (PMID 29854830, 2018). "Studies such as these underscore the potential of targeting the IL1β pathway in slowing down atherosclerosis progression." (PMID 29988570, 2018). "In this study, the gender differences in circulating IgG antibodies to inflammatory cytokines were observed, so that up-regulation of anti-TNFα, anti-IL1α, and anti-IL1β IgG levels were more likely to occur in female than male patients with atherosclerosis." (PMID 30479572, 2018). "There is a role for both cholesterol and IL1β in this process, because cholesterol crystals activate NLRP3, leading to IL1β production, and activated macrophages are present as foam cells in atherosclerosis." (PMID 29463677, 2018). "The differential induction and distinct roles of IL-1α and IL-1β in fat-induced vascular responses and atherosclerosis have recently been highlighted." (PMID 29329335, 2018). "Meanwhile, evidence shows that chronic nicotine exposure augments atherosclerosis by enhancing the production of pro-inflammatory cytokines, including IL-1β and TNF-α." (PMID 29416034, 2018). "Controlling the biology of Interleukin-1 beta (IL-1β), which drives the progression of atherosclerosis, leading to cardiovascular complications, has been of particular interest." (PMID 29997514, 2018). "The CANTOS trial targeted IL-1β in atherosclerosis patients and the intervention reduced inflammation and cardiovascular events." (PMID 30618774, 2018). "Increased levels of various inflammatory factors in the circulation that play a critical role in the pathogenesis of atherosclerosis, including IL-1β, IL-6, MCP-1 and TNF-α, were detected." (PMID 30413028, 2018). "Andrographolide (10 and 20 mg/kg, p.o. over 12 weeks) in P. gingivalis-induced atherosclerosis male white New Zealand rabbits (n = 6) reduced in IL-1β and -6, and CRP." (PMID 28878680, 2017). "The specific role of the two IL‐1α and IL‐1β isoforms in atherosclerosis development is still under debate." (PMID 28409825, 2017). "Like IL-1β, IL-1α is involved in a number of disease states including stroke, haemorrhage, cancer, and atherosclerosis." (PMID 28067797, 2017). "Since several studies have shown that IL-1β contributes to the progression of atherosclerosis, it is expected that the deficiency of NLRP3 inflammasomes prevents atherosclerosis." (PMID 29259717, 2017). "NF-kB controls the expression of genes that direct the initiation and progression of atherosclerosis or fibrosis, including cytokines, such as TNFα or IL-1β." (PMID 28272516, 2017). "Herein, ICAM-1, VCAM-1, MCP-1, TNF-α, IL-1β, and MMPs-9, which participate in initial and later stages of atherosclerosis, will be more elaborately discussed." (PMID 29038791, 2017). "CX3CL1 induces tumor necrosis factor alpha (TNF-α), interferon gamma, and interleukin 1 beta (IL-1β) production in chronic obstructive pulmonary disease, pulmonary hypertension, atherosclerosis, RA, HIV infection, and cancer." (PMID 29268768, 2017).
atherosclerosis (continued). "Atherosclerosis is a chronic inflammatory disease that is promoted, among others, by pro-inflammatory cytokines such as IL-1β and IL-18 produced by NLRP 3 inflammasome." (PMID 28950870, 2017). "Cholesterol crystal (CHC), a hallmark of atherosclerosis, initiate inflammation via nod-like receptors nucleotide-binding domain and leucine-rich repeat pyrin-3 domain (NLRP3) inflammasome leading to IL-1β and TNF production." (PMID 29133791, 2017). "In atherosclerosis, the main three proposed mechanisms are dampened inflammasome/IL-1β activation, accelerated removal of protein aggregates and increased cholesterol efflux." (PMID 28589926, 2017). "IL-1β is a pro-inflammatory cytokine and has been suggested to be involved in the pathogenesis of atherosclerosis and vascular and myocardial injury." (PMID 26790748, 2016). "The NLRP3 inflammasome recognizes many endogenous materials as danger signals and triggers the release of strong pro-inflammatory cytokines including active IL-1β, thus contributing to diverse diseases as atherosclerosis, Alzheimer’s disease, and T2 diabetes." (PMID 27965665, 2016). "Many kinds of inflammatory cytokines, such as IL-1β, are involved in inflammatory response of atherosclerosis." (PMID 27110561, 2016). "Ultimate evidence regarding the efficacy and safety of IL-1β neutralization in humans with established atherosclerosis will emerge from sufficiently powered clinical endpoint trials such as CANTOS." (PMID 27032103, 2016). "Among other cytokines, IL-1β and IL‐18 are known to be an important modulators in artery wall inflammation and acceleration of atherosclerosis." (PMID 26523150, 2015). "Inflammation is an important risk factor for atherosclerosis and EAT secretes various cytokines including IL-1β, IL-6, and TNF-α, the levels of which were significantly higher in patients with coronary artery disease." (PMID 25887962, 2015). "Cytokines such as IL-1β, IL-18, IL-6 and TNF-α are key mediators in chronic vascular inflammatory response underlying several aspects of atherosclerosis and cardiovascular disease." (PMID 26600018, 2015). "The plasma levels of IL-1β in mice with atherosclerosis were also significantly higher than those observed in the control group." (PMID 25761252, 2015). "Activation of the NLRP3 inflammasome and hypersecretion of IL-1β are known to be involved in a variety of acute and chronic disorders including diabetes, atherosclerosis, gout, chronic kidney disease and Alzheimer’s disease." (PMID 25655831, 2015). "In vivo, the knockdown of P2X7R in apoE−/− mice significantly delayed the development of atherosclerosis with lower plasma levels of IL-1β." (PMID 25761252, 2015). "As a second aim of our study, among the confirmed IL-1β-up-regulated genes, we then focused our attention on those of relevance for atherosclerosis and maximally counter-impacted by DHA treatment." (PMID 26114549, 2015). "Clinical and in vivo evidence accumulated over the previous years has suggested a pro-inflammatory role for IL-1β in atherosclerosis." (PMID 26098632, 2015). "Atherosclerosis is a hyperlipidemia-induced chronic inflammatory process of the arterial wall, involving interleukins (ILs) such as IL-1β, IL-6, tumor necrosis factor (TNF)-α, and C-reactive protein (CRP)." (PMID 25664324, 2015). "Macrophages produce abundant amounts of pro-inflammatory cytokines, such as TNF-α, IL-6, and IL-1β, to promote atherosclerosis." (PMID 26045945, 2015). "There were no positive correlations of the other inflammatory markers evaluated (TNF-α, IL-6, IL-1β, homocysteine, hsCRP) in relation to the imaging markers of subclinical atherosclerosis." (PMID 26382922, 2015).
atherosclerosis (continued). "When IL-1β binds to CD121a, a signaling cascade is initiated that eventually leads to atherosclerosis." (PMID 26098632, 2015). "The main inflammatory cytokines participating in atherosclerosis, IL-1β, TNF-α, MCP-1 and MMP-2, were detected in the plaque." (PMID 24755612, 2014). "Atherosclerosis induced by a high-fat diet was characterized by a gradual increase in the levels of the inflammatory cytokines IL-1β, IL-6, MCP-1 and TNF-α compared with the control group." (PMID 25120600, 2014). "Atherosclerosis involves the release of inflammatory cytokines, such as interleukin 1-β (IL1-β) and tumor necrosis factor-α (TNFα) which participate in pro-inflammatory signaling." (PMID 24755612, 2014). "In particular, we found high levels of IL-1β, TNF-α, IFNγ and CD40L, all of which have been associated with the progression of atherosclerosis." (PMID 25548922, 2014). "It is notable that IL-1β, IL-18, TNF-α, and IFN-γ play critical pathogenic roles in atherosclerosis, and increased levels of these cytokines are associated with the onset of ACS." (PMID 24733959, 2014). "Supporting evidence for a role of IL-1β in atherogenesis has been obtained from experiments in atherosclerosis-prone mice." (PMID 24244322, 2013). "IL-1α and IL-1β contribute to the development of vascular damage and atherosclerosis by stimulating cell proliferation and differentiation and the release of matrix-degrading enzymes." (PMID 24063019, 2013). "As has mentioned in Background, TNF-α and IL-1β are two important inflammatory factors in the progression of atherosclerosis." (PMID 23895132, 2013). "Platelets chemokines (e.g. RANTES, PF4, SDF-1, MCP-1, CXCL5, CXCL7) and newly synthesized active cytokine-like factors [e.g. IL-1β, CD40 ligand (CD40L), β-thromboglobulin] are implicated in the development of atherosclerosis." (PMID 23372649, 2013). "Macrophages and IL1β are found in all stages of atherosclerosis development and contribute to local inflammatory responses." (PMID 23560095, 2013). "Once activated, macrophages produce an array of proinflammatory cytokines such as TNFα, IL-12, IL-6, IL-1β, and leukotrienes that drive inflammation during atherosclerosis." (PMID 23401644, 2013). "Interleukins are key mediators of the systemic inflammatory response, and especially, IL-1β has been known to play an important role in atherosclerosis." (PMID 23825600, 2013). "IL-1β, released by macrophages, platelets, and injured endothelium, plays a central role in the inflammatory response and its related atherosclerosis." (PMID 23029154, 2012). "Monocytes/macrophages infiltrate atherosclerotic lesion areas and increase the expression of inflammatory genes, such as TNF-α, IL-1β and iNOS, which play an important role in development and progression of atherosclerosis." (PMID 23243449, 2012). "Immune-activated macrophages express a variety of inflammatory genes, such as iNOS, COX-2, TNF-α, and IL-1β, which are major contributing factors in the pathogenesis of atherosclerosis." (PMID 23243449, 2012). "For example, LDL-receptor-deficient mice (genetically prone to atherosclerosis) that are reconstituted with bone marrow cells from mice that lack NLRP3, ASC, or IL-1β are remarkably resistant to plaque formation." (PMID 23087690, 2012). "This indicates that our findings are transferable to aortic endothelial cells, which are the most relevant model cell type for atherosclerosis studies, and that the effect is not limited to the effect of IL-1β." (PMID 22815786, 2012). "The pro-inflammatory cytokines TNF-α, IL-1β, IL-6, and other acute phase proteins such as serum amyloid A (SAA) and C-reactive protein (CRP) have been associated with atherosclerosis or increased risk of cardiovascular disease." (PMID 21249123, 2011). "The cytokines TNF-α, IL-1β IL-6, and IL-8 are important in vascular inflammation and atherosclerosis." (PMID 21249123, 2011).
atherosclerosis (continued). "diHPA exerted anti-inflammatory properties by reducing the secretion of pro-inflammatory cytokines, TNF-α, IL-1β and IL-6, involved in the early stages of atherosclerosis from lipopolysaccharide (LPS)-stimulated human peripheral blood mononuclear cells (PBMC)." (PMID 21272305, 2011). "In atherosclerotic coronary arteries, IL-1β levels have been shown to correlate with disease severity, and knocking out IL-1β in atherosclerosis-prone ApoE−/− mice leads to attenuation of disease development." (PMID 20668705, 2010). "In atherosclerosis, the inflammasome-mediated IL-1β release would promote an inflammatory milieu and thus drive lesion progression." (PMID 20668705, 2010). "Several studies have shown that pro-inflammatory cytokines, such as tumor necrosis factor (TNF)-α, interleukin (IL)-1β, and IL-6, play an important role in the development of atherosclerosis." (PMID 20946675, 2010). "This is in agreement with previous studies that showed decreased atherosclerosis in IL-1β−/− and IL-1α−/− mice fed a high cholate diet and with data from a heterozygote Apoe−/− model." (PMID 19347044, 2009). "Monocytes, their progeny such as dendritic cells and osteoclasts and products including tumor necrosis factor (TNF)-α, interleukin (IL)-1α and IL-1β play important roles in cancer, inflammation, immune response and atherosclerosis." (PMID 19715605, 2009). "Non-alcoholic fatty liver disease and atherosclerosis may share a common pathogenesis involving chronic IL-1β-induced inflammation." (PMID 41811513, 2026). "This role of inflammation in atherosclerosis is further supported by evidence that targeting the proinflammatory cytokine interleukin-1β (IL-1β) with canakinumab reduced recurrent cardiovascular events by 15% in patients with established atherosclerosis, irrespective of lipid levels." (PMID 40454002, 2025). "Notably, IL-1β plays a crucial role as a mediator of the inflammatory process, further contributing to vascular inflammation and the development of atherosclerosis." (PMID 41230308, 2025). "Additionally, impaired triglyceride metabolism stimulates the secretion of pro-inflammatory cytokines, such as TNF-α, IL-6, and IL-1β, leading to systemic inflammation and endothelial dysfunction—both of which accelerate the progression of atherosclerosis." (PMID 40077648, 2025). "IL-1β can lead to fiber atherosclerosis, and plaque injury, and reduce inflammatory responses." (PMID 40427511, 2025). "The cardiovascular risk presented by DNMT3A- and TET2-mutant CHIP can be mitigated by an inhibitory IL-6 receptor gene variant (IL6R p.Asp358Ala), highlighting the key role of the mediators of inflammation NLRP3, IL-1β and IL6 in CHIP-associated atherosclerosis." (PMID 40076674, 2025). "Additionally, interleukin-1 beta (IL-1β) is a key regulator of the inflammatory cascade in atherosclerosis, promoting endothelial dysfunction and smooth muscle cell proliferation." (PMID 40217801, 2025). "The chronic inflammatory environment present in atherosclerosis, marked by elevated cytokines such as IL-1β, IL-6, TNF-α, and interferon-gamma (IFN-γ), promotes oxidative stress and DNA damage in HSCs, particularly given their high turnover rates required to sustain lifelong hematopoiesis." (PMID 41516113, 2025). "Moreover, the inflammatory environment of atherosclerosis, enriched with interleukin-1 beta (IL-1β) and oxidative stress products, can promote autoantigen exposure and neo-epitope formation." (PMID 40926914, 2025). "The deletion of IL-1β led to a 33% reduction in total atherosclerotic lesions in high-fat diet (HFD)-fed apolipoprotein E deficient (apoE−/−) mice, demonstrating the effectiveness of anti-inflammatory treatment in improving atherosclerosis." (PMID 40422906, 2025). "Similarly, interleukin-1β (IL-1β), a potent pro-inflammatory cytokine, plays a pivotal role in arterial calcification, particularly within the context of atherosclerosis." (PMID 40241989, 2025).